AMH (anti-Mullerian hormone)
Diseases named in the same sentence as AMH in open-access papers (continued):
Sharing a sentence is not in itself a finding about the gene and the disease.
Infertility (continued). "Clinical outcome was co-determined by serum AMH, serum progesterone, rank of stimulation attempt, duration of infertility, peak level of serum E2 and the number of oocytes retrieved." (PMID 31110647, 2018). "In summary, the results of this study suggest that higher psychological stress, measured as SAA levels, was related to a lower serum AMH level in infertile women." (PMID 28693593, 2017). "The SAA level was significantly, and negatively correlated with AMH levels in infertile women (r = −0.315, P = 0.000; adjusted for age, r = −0.336, P = 0.000)." (PMID 28693593, 2017). "Featureswith the same score are considered to be equallysignificant, like infertility duration and anti-Mullerianhormone (AMH) testing features." (PMID 28868840, 2017). "In this study, we found that there was a significant correlation between psychological stress and decreased AMH levels for infertile women." (PMID 28693593, 2017). "For the first time, we are reporting AMH levels in Pakistani infertile population and predict a cut-off value of 1.37ng/ml that discriminate good and bad responders." (PMID 27648045, 2016). "We strongly suggest incorporation of AMH evaluation in baseline assessment of ovarian reserve, especially in younger infertile patients as timely IVF treatment can improve the pregnancy outcomes in these populations." (PMID 27648045, 2016). "The mean BMI, FSH and AMH levels of one hundred and sixty-six infertile females recruited in this study is summarized in Table-I." (PMID 27648045, 2016). "In clinical practice, AMH evaluation has guided infertility care physicians to modify the dose of medication, avoiding the risk of OHSS or cycle cancellation due to nonresponsiveness." (PMID 26977116, 2016). "Based on AMH levels, the patients with tubal factor infertility were divided in three groups of normal, low and high AMH levels." (PMID 28066836, 2016). "We suggest incorporation of AMH in baseline assessment of infertile females, who are falsely advised to postpone interventions based on their age and normal FSH levels." (PMID 27648045, 2016). "The serum level of AMH was significantly lower in infertile women with high total sexual distress scores (1.4 vs. 7.6 ng/mL (p<0.001))." (PMID 28913070, 2015). "In infertile women, age of woman, age of partner, and serum AMH levels are related with the hope of women to have a child despite an association with sexual distress." (PMID 28913070, 2015). "Overall there was a significantly lower mean AMH serum level in infertile women compared to the control group (p=0.002)." (PMID 25918589, 2015). "Although the mean serum AMH levels consistently decreased with increasing age in both the infertile and control groups, the reduction seen in the infertile group was more (p<0.05)." (PMID 25918589, 2015). "The mean AMH serum levels from differentages of infertile and control group (fertile women) decreased with increasing age.However, this reduction was greater in the infertile group." (PMID 25918589, 2015). "In a retrospective study, 177 infertile patients were as-sessed for AMH in serum and follicular fluid (FF) on the day of follicular puncture(FP), between 2012 and 2013 in Kiel, Germany." (PMID 26246873, 2015). "They reported that serum AMH levels decreased over time in both infertile and healthy control women, which was similar to the results of our study." (PMID 25918589, 2015). "Because such predictions are of paramount importance when counselling patients who are undergoing assisted reproductive procedures, AMH levels should be determined before embarking on infertility treatments." (PMID 26059906, 2015). "The study allows for this conclusion for a number of reasons: Based on very high AMH levels and hyperandrogenemia at young ages, here investigated young infertility patients, unquestionably, had been correctly assigned a diagnosis of PCOS." (PMID 26156856, 2015).
Infertility (continued). "The groups were not significantly different with respect to age, etiology of infertility, BMI, AMH, or AFC." (PMID 26216410, 2015). "Pre-stimulation menstrual cycle day-3 hormonal indices including basal AMH values were measured in 105 infertile women aged 32.5 ± 4.3 years." (PMID 26357853, 2015). "We suggest that infertile patients undergoing COH with top and low quartile basal AMH values are at high risk for OHSS and poor ovarian response, respectively." (PMID 26357853, 2015). "Serum level of AMH was significantly lower in infertile women with high total sexual distress scores (1.4 vs. 7.6 ng/mL (p<0.001))." (PMID 28913070, 2015). "Last, this review will explain the utility of serum AMH assay in the management of infertility in women with PCOS and its utility as a marker of treatment efficiency on PCOS symptoms." (PMID 26691645, 2015). "As the table demonstrates, mean age, body mass index (BMI), FSH, AMH and primary infertility diagnoses of both groups were similar." (PMID 25048047, 2014). "In summary, AMH is now our main method of determining ovarian reserve and selecting our pretreatment counseling and choice of infertility treatment." (PMID 35761734, 2014). "This study demonstrates that serum AMH level is an independent predictor of ongoing pregnancy in infertile women." (PMID 35761734, 2014). "Age was similar to the development cohort, with AMH being significantly higher and duration of infertility shorter in the EV cohort." (PMID 23294733, 2013). "Our results showed that AMH was strongly expressed in the ovary of infertile mice three weeks to two months after transplantation." (PMID 24406076, 2013). "Our results demonstrate gradually declining AMH levels with age in fertile women, similar to declines reported in infertile populations." (PMID 21777422, 2011). "Among infertile patients, substantially higher percentages of women at both extremes of AMH values (i.e., diminished ovarian reserve and polycystic ovary syndrome) are observed." (PMID 21777422, 2011). "They, however, also show substantially lower AMH levels postpartum than reported in infertile patients." (PMID 21777422, 2011). "The prospective assessment of as-FSH and -AMH, in combination with female age, thus, can help in predicting oocyte yields in women with infertility." (PMID 20565808, 2010). "It is known that Sox9 inhibits Wnt signaling in chondrocytes and that abnormal activation of the Wnt pathway in mouse Sertoli cells leads to degeneration of tubules and infertility, a phenotype reminiscent of the one reported for AMH-Cre Sox9flox/flox mice." (PMID 21182756, 2010). "The infertility duration, female age, female BMI, female basal hormone levels, female AMH, male BMI, COS protocol, number of retrieved oocytes, fertilization, and number of transplanted embryos were similar between the two groups, reducing the influence of other factors on clinical outcomes." (PMID 40416621, 2025). "Moreover, infertile women with ovarian endometriomas had lower AMH concentrations and greater prolactin levels." (PMID 40002761, 2025). "The baseline AMH value for the infertile female patients with obesity (n=36) was 3.6 ± 3.80 ng/ml." (PMID 40463745, 2025). "After adjusting for embryo quality, age, BMI, AMH, duration of infertility, and endometrial thickness, multivariable analysis confirmed that the hysteroscopy group had a significantly higher clinical pregnancy rate (OR: 1.51, 95% CI: 1.142–1.997, P = 0.004) compared to the non-hysteroscopy group." (PMID 41312455, 2025). "Compared with women in the lower TyG-BMI quartiles, women in the higher quartiles tend to be older, have higher BMI, SBP, diastolic blood pressure (DBP), TG, TC, LDL and FBG, longer infertility duration, but lower AMH, basal FSH, basal luteinizing hormone (LH) and HDL (all P trend < 0.05)." (PMID 40810075, 2025).
Infertility (continued). "Research indicates that there is a negative correlation between age and AMH levels in healthy women and in those experiencing infertility due to various causes." (PMID 39336427, 2024). "However, little attention has been paid to the significance of AMH level in predicting natural conception following infertility surgery." (PMID 39015183, 2024). "However, a wide overlap of AMH values between controls and infertile men precludes this hormone from being a useful marker of spermatogenesis." (PMID 39032500, 2024). "Before matching, the NC and HRT groups had statistically significant differences in terms of female age, infertility duration, infertility type, gravity, parity, number of miscarriages, BMI, AMH, number of AFC, number of embryos transferred, and type of embryos transferred." (PMID 39092281, 2024). "This may be related to a “change point issue”, wherein serum and follicular fluid levels of AMH are negatively correlated with Vit D to ~30 ng/mL and thereafter show a positive insignificant relationship with tubal factor infertility patients." (PMID 40777956, 2024). "Recent data show that with an AMH threshold of 3.2 ng/mL, 34.8% are classified as phenotype D, The similarities such as secondary amenorrhea, PCO morphology on ultrasound/increased AMH levels, and infertility make it very difficult to differentiate between the two conditions." (PMID 38592037, 2024). "Interestingly, these young men from the general population had higher serum AMH (using same assay) and better semen quality than our cohort of infertile men." (PMID 36855109, 2023). "Interestingly, the sister of the affected female in this latter study also carried both variants but presented with normal menses and hormonal levels except for low AMH and infertility." (PMID 38737775, 2023). "Before PSM, age, infertility type, BMI, AMH, basal FSH, basal LH, basal testosterone, AFC, as well as number of giving birth and number of pregnancies before IVF/ICSI were statistically different between PCOS and non-PCOS clinical pregnancy cycles (all P < 0.05)." (PMID 37045897, 2023). "A total of 1,675 cycles were included in the study, and the Kruskal-Wallis H (K) test was performed on female age, infertility duration, female body mass index (BMI), anti-mullerian hormone (AMH), basal follicle-stimulating hormone (FSH) level, and endometrial thickness." (PMID 38027138, 2023). "Duration of infertility and serum levels of AMH were increased by an increment of BMI." (PMID 38370492, 2023). "Thus, in this study, we aimed to explore the predictive power of AMH in infertile women with PCOS/PCOM and determine the BMI-stratified AMH thresholds for diagnosing PCOS/PCOM." (PMID 36726106, 2023). "Based on previous studies suggesting that AMH concentration varies between women of different ethnic backgrounds, we examined the optimal cutoff value of AMH concentration to diagnose polycystic ovarian syndrome in Chinese infertility women from a single center." (PMID 36726106, 2023). "In the sequential ET group, the average age, infertility duration, AMH level, FSH level, number of previous failed cycles, endometrial thickness and high-quality cleavage-stage embryo rate were equivalent in patients with D5 or D6 blastocyst transfer (P > 0.05)." (PMID 37990167, 2023). "Our study shows a correlation between TSH and AMH values in a population of infertile women." (PMID 37925426, 2023). "The average age, body mass index (BMI), infertility duration, anti-Mullerian hormone (AMH) level, base follicle stimulating hormone (bFSH) level and infertility factors in the sequential ET and conventional ET groups were not significantly different (P > 0.05)." (PMID 37990167, 2023). "But for patients with polycystic ovarian morphology, AMH may be a good prognostic marker of therapeutic efficiency in the treatment of infertility and polycystic ovary syndrome." (PMID 37381009, 2023).
Infertility (continued). "This study shows that low serum AMH may serve as a marker for impaired Sertoli cell function and poor sperm production in infertile men." (PMID 36855109, 2023). "No confounding factors were adjusted in the crude model; Adjusted model 1 corrected age, BMI, infertility years and endometrial thickness on the day of ET, and adjusting model 2 corrected AMH, bFSH, number of failed cycles and number of embryos transferred on the basis of adjusting model." (PMID 37990167, 2023). "In this retrospective and cross-sectional study, 70 patients with unilateral and bilateral endometrioma were recruited and compared with 70 age-matched infertile patients as the control group in terms of AMH before ovum pick-up, embryo quality as well as pregnancy outcome." (PMID 37344833, 2023). "In the general infertile population, age as a marker of ovarian function was found to have a prognostic value because age showed a strong correlation with all the markers of ovarian function like AMH, AFC, estradiol, and FSH." (PMID 36128562, 2022). "We describe a protocol for a planned RCT aimed at evaluating whether treatment with denosumab can improve the semen quality in infertile men selected by using serum AMH as a positive predictive biomarker." (PMID 35733213, 2022). "Moreover, infertility patients with endometriosis showed lower AMH level compared to women with a primary diagnosis of male factor infertility." (PMID 34405378, 2022). "This RCT aims to assess whether treatment with denosumab can improve semen quality in infertile men selected by serum AMH as a positive predictive biomarker." (PMID 35733213, 2022). "Notably, our study confirmed that AMH levels, duration of infertility, and a polycystic ovarian morphology (PCOM) are factors associated with a follicle maturation in women diagnosed with PCOS undergoing stimulation with letrozole." (PMID 35566720, 2022). "In the univariate binary regression models, only a longer duration of infertility, absence of polycystic ovarian morphology, and lower AMH serum levels were associated with obtaining a dominant follicle after letrozole stimulation." (PMID 35566720, 2022). "In this study, univariate logistic regression analyses were performed and seven potential factors associated with clinical pregnancy, including age, AMH, AFC, overall ART attempts, infertility duration, progesterone on HCG day, and GVBD rate, were included in a well-fitted multivariate model." (PMID 36699025, 2022). "On the other hand, some studies on populations of women with infertility, yielding negative association between serum vitamin D and AMH concentrations." (PMID 35220479, 2022). "This RCT aims to assess whether treatment with denosumab can improve spermatogenesis in infertile men selected by serum AMH as a positive predictive biomarker." (PMID 35733213, 2022). "The cause of infertility and initial AMH level was not statistically significant in both groups (p = 0.86)." (PMID 35566454, 2022). "In conclusion, this study shows that female age ≥ 35, poor sperm quality, primary infertility, ART failure history, minimal-stimulation and natural method, numbers of retrieved oocytes < 5, IVF (compared with ICSI), and low level of AMH, are associated with higher risks for fertilization disorders." (PMID 35518924, 2022). "This suggests that a single AMH measurement may lead to an inaccurate assessment of the FOR leading to clinical consequences in infertility patients." (PMID 36128562, 2022). "Furthermore, the duration of infertility, as well as levels of AMH, was markedly higher in the ≤37‐year group than in the ≥38‐year group." (PMID 34995407, 2022). "Thus, to assess the predictive ability of AMH for IVF outcomes in specific subpopulations of infertility patients, we separately analyzed women with PCOS." (PMID 35236324, 2022).
Infertility (continued). "The efficacy of ovulation induction through letrozole 2.5 mg for five days in infertile, anovulatory PCOS women is associated with lower serum AMH levels, whereas parameters of calcium metabolism, such as serum calcium, 25OHD3, and PTH do not seem to be predictive." (PMID 35566720, 2022). "The predictive value of AMH for ART outcomes may be markedly different in specific subpopulations of infertility patients." (PMID 35236324, 2022). "After controlled for confounding factors: Age, Infertility duration, AMH, Basal serum FSH, LH, E2, P, T, AFC, BMI, Gn used dosage, Gn used duration, the results showed that TSH was negatively correlated with oocyte maturation of each PCOS patient [β = -0.124, P = 0.013,95%CI (-0.027 ~ -0.003)]." (PMID 36056438, 2022). "Serum AMH is used as a clinical marker of ovarian reserve in the treatment of infertility." (PMID 33855196, 2021). "Furthermore, positive VD effects on AMH levels were found in a prospective study including infertile women with diminished ovarian reserve." (PMID 33562394, 2021). "The age, body mass index (BMI), duration of infertility, infertility factors, anti-Müllerian hormone (AMH), antral follicular count, basic FSH level and days of estrogen supplementation prior to luteal phase induction, and the endometrial thickness were comparable between the two groups." (PMID 34733238, 2021). "(OR = 0.48; 95% CI = 0.28‐0.82), suggesting that if age, infertility duration, past live‐births, and AMH were equal in the two groups, the odds for a live‐birth after one cycle of IVF in couples with UI1 would be reduced to half when compared with couples with a known factor infertility." (PMID 33850452, 2021). "The miRNAs that have been validated in phase III by RT-qPCR and correlated with AMH level (26 miRNAs) were tested for their suitability as biomarkers for assessing the ovarian reserve of a woman presenting at an infertility clinic." (PMID 34172798, 2021). "The univariate analysis showed that advanced age, decreased AMH level, and infertility were associated with no pregnancy or with miscarriage." (PMID 34646081, 2021). "Data were analyzed to determine whether circulating miRNA profiles correlate with the level of serum AMH and can serve as potential biomarkers for predicting ovarian reserve in women attending infertility treatment." (PMID 34172798, 2021). "In addition, the positive effects of vitamin D on AMH levels decreased in a prospective study including infertile women with diminished ovarian reserve." (PMID 34154571, 2021). "There are some data showing that psychological stress is related to a decreased AMH level in infertile women with PCOS and this psychological stress may affect the ovarian reserve." (PMID 34108885, 2021). "However, based on our findings, we suggestthat it is possible to tailor a safe stimulation protocol fornormal-ovulatory infertile patients who have a polycysticovarian appearance and an AMH level over 4.95 ng/ml." (PMID 33687164, 2021). "Our data show that serum T levels are positively associated with serum AMH levels and suggest that androgen insufficiency may be a potential risk factor for DOR; androgen excess may lead to EOR in infertile women." (PMID 33737663, 2021). "Chinese women had a higher number of oocytes after ovarian stimulation using a standardized stimulation regimen compared with Caucasian women undergoing IVF after controlling for age, BMI, AFC and AMH despite presenting later after a longer duration of infertility." (PMID 34895264, 2021). "Although a small RCT among VD-deficient infertile PCOS women reported a positive VD effect on AMH levels, data from large RCTs are lacking." (PMID 33562394, 2021). "Serum AMH levels are utilized as a marker of ovarian reserve in clinical infertility care." (PMID 33263001, 2020).